PRDM16 (PR/SET domain 16)
Diseases named in the same sentence as PRDM16 in open-access papers (continued):
Sharing a sentence is not in itself a finding about the gene and the disease.
acute myeloid leukemia (12 papers, 2008 to 2026). Acute myeloid leukemia (AML) is a group of neoplasms arising from precursor cells committed to the myeloid cell-line differentiation. "The common nodes for solid and lymphatic–hematopoietic cancers have also been previously associated to cancer, for instance PRDM16 was related to acute myeloblastic leukemia." (PMID 33632303, 2021). "PR domain-containing 16 gene (PRDM16) is a known oncogene implicated in acute myeloid leukaemia (AML) and osteosarcoma Tensin 1 gene (TNS1) is the only gene present in the relevant FMCR, and TNS1 overexpression in vitro was previously shown to significantly promote cell migration in fibroblasts." (PMID 24367615, 2013). "In acute myeloid leukemia (AML), PRDM16 overexpression is linked to specific cytogenetic risk groups and poor prognosis." (PMID 41566085, 2026). "Interestingly, a study in acute myeloid leukemia cells demonstrated that Prdm16 overexpression activates oxidative phosphorylation." (PMID 40683857, 2025). "Expression of high levels of a truncated form of Prdm16 that does not encode the PR domain (called sPrdm16 or Mel1s) is associated with acute myeloid leukaemia (AML) in humans and causative of AML in mouse." (PMID 19050759, 2008). "The PRDM16 gene codes for a zing-finger protein containing a DNA-binding PRDI-BF1/RIZ homologous (PR) domain, and it is commonly rearranged in hematologic malignancies of myeloid lineage, mainly myelodysplastic neoplasms (MDS) and/or acute myeloid leukemia (AML)." (PMID 40933896, 2025).
Hepatic steatosis (8 papers, 2017 to 2025). Steatosis is a term used to denote lipid accumulation within hepatocytes. "Interestingly, deletion of Prdm16 by adiponectin-Cre leads to a similar phenotype, that is, selective defect in iWAT browning, high-fat diet-induced, body weight-independent hepatic steatosis, and glucose intolerance." (PMID 28701693, 2017).
lung cancer (8 papers, 2017 to 2024). A malignant neoplasm involving the lung. "In lung cancer, the high methylation signature of the PRDM16 gene caused a significant reduction of its expression." (PMID 33291744, 2020). "Another study indicated that relatively high expression of PRDM16 in patients with nonsmall cell lung cancer was associated with a preferable survival score." (PMID 33291744, 2020). "Studies have shown that the PRDM2, PRDM5, and PRDM16 promoters in lung cancer cells are methylated, resulting in suppressed expression." (PMID 39468462, 2024). "The loss of PRDM family members, including PRDM16, in kidney and lung cancer suggested that PRDM16 is involved in the pathogenesis of multiple cancers." (PMID 37534217, 2023). "Apart from the study in hematologic neoplasm, recent research has explored controversial functions of PRDM16 gene in solid cancers, such as gastric, prostate, esophageal squamous cell, and lung cancers." (PMID 34796170, 2021). "To assess PRDM16 expression in lung cancer patients, we first analyzed the gene expression datasets of human lung adenocarcinomas and lung squamous cell carcinomas." (PMID 30683132, 2019). "Kaplan-Meier plotter database was used to analyze the overall survival of patients with lung cancer stratified by PRDM16 expression." (PMID 30683132, 2019). "UALCAN database, immunoblotting and immunohistochemistry analysis were used to assess PRDM16 expression in lung cancer patients." (PMID 30683132, 2019). "The demethylation drug 5-aza-2′-dC upregulates PRDM16 expression and suppresses growth of lung cancer cells." (PMID 27893424, 2017). "For example, PRDM16 is often methylated in lung cancer cells, with downregulated protein expression." (PMID 27893424, 2017). "Only PRDM16 and MTHFD1L are significantly enriched targets in miR-C2; miR-133, which is present in miR-C2, is reported to directly target and downregulate PRDM16 to regulate fat cell differentiation, and PRDM16 overexpression has been reported to inhibit EMT in lung cancer models." (PMID 38097740, 2024).
atherosclerosis (7 papers, 2018 to 2026). A disease characterized by the build-up of fatty material and calcium deposition in the arterial wall resulting in partial or complete occlusion of the arterial lumen. "PRDM16 is downregulated during SMC modulation in atherosclerosis, and genetic loss of Prdm16 in mice results in the development of fibrous lesions with reduced lipid content." (PMID 41107595, 2025). "The enhanced fibrotic profile and increased fibrous cap formation observed in lesions from Prdm16-deficient mice are phenotypic features associated with a lower risk of rupture in human atherosclerosis." (PMID 41107595, 2025). "Next, we focused on the effects of Prdm16 deficiency in SMCs during atherosclerosis." (PMID 41107595, 2025). "To determine how PRDM16 loss in SMCs affects atherosclerotic lesion development, we induced atherosclerosis in control and SMC-cKO mice using AAV8-mediated delivery of mPCSK9 D377Y coupled with Western diet feeding under thermoneutral housing conditions (30 °C) for 12 weeks." (PMID 41107595, 2025). "In addition, rare PRDM16 coding variants in the UK Biobank cohort are associated with atherosclerosis-associated conditions, including coronary artery disease, stroke and CVD." (PMID 41107595, 2025). "In addition, deletion of Prdm16 in adult SMCs increased the proportion of cells undergoing atherosclerosis-associated synthetic modulation." (PMID 41107595, 2025). "To assess how Prdm16 deletion in adult SMCs affects atherosclerosis, we induced plaque formation in control and SMC-iKO mice 1 week after tamoxifen treatment via injection of AAV8-mPCSK9 D377Y and Western diet feeding for 12 weeks." (PMID 41107595, 2025). "Single-cell RNA sequencing (scRNA-seq) analyses revealed that loss of Prdm16 upregulated synthetic genes across all SMC subpopulations and promoted the emergence of synthetic modulated cells during atherosclerosis." (PMID 41107595, 2025). "To investigate the role of PRDM16 in SMC phenotypic modulation during advanced atherosclerosis, we used our native tissue scRNA-seq approach." (PMID 41107595, 2025). "Acetylation of PPARγ at K268/K293 increases atherosclerosis through upregulating ABCA1, ABCG1, and NcoR but inhibiting PRDM16, while deacetylation of PPARγ at K268 and K293 alleviates atherosclerosis." (PMID 35309069, 2022). "Consequently, therapeutic modulation of PRDM16 holds significant potential to attenuate the progression of atherosclerosis, hypertension, and TAA, highlighting its value as a novel target in vascular disease management." (PMID 41528566, 2026). "We then assessed PRDM16 expression in mouse atherosclerosis." (PMID 41107595, 2025). "The pathways that downregulate PRDM16 expression during atherosclerosis are unknown but of substantial interest." (PMID 41107595, 2025). "Importantly, several preclinical studies have suggested a role for PRDM16 in the initiation/progression of arterial-restricted diseases, such as atherosclerosis, coronary artery disease (CAD), and abdominal aortic aneurysms (AAAs)." (PMID 40439125, 2025). "Smooth muscle–specific Prdm16 deletion leads to maladaptive SMC phenotypic switching, ECM remodeling, and inflammation, resulting in AAA formation and the development of atherosclerosis." (PMID 41528566, 2026). "Collectively, these data demonstrate that PRDM16 is highly expressed in arterial SMCs and downregulated during SMC modulation and fibrotic cap formation in both human and mouse atherosclerosis." (PMID 41107595, 2025). "We found that PRDM16 is highly expressed in arterial SMCs and downregulated during SMC modulation in mouse and human atherosclerosis." (PMID 41107595, 2025). "In this study, we investigated the role of PRDM16 in regulating SMC identity and atherosclerosis." (PMID 41107595, 2025). "Importantly, ApoE−/− atherosclerosis mice had decreased expression of UCP1, PGC1α, PRDM16, Cidea, and RPS3A." (PMID 30131868, 2018).
breast cancer (7 papers, 2020 to 2024). A primary or metastatic malignant neoplasm involving the breast. "In support of this possibility, we demonstrated that silencing of either DLG5 or PRDM16 abolished multiple LINC00589-induced effects in HER2-positive breast cancer." (PMID 36309503, 2022). "Further, we constructed PRDM16 overexpression vector to confirm the regulatory effect of PRDM16 on MUC4 levels in breast cancer cells, and the efficiency was tested by qRT-PCR assay." (PMID 36309503, 2022). "Based on the CNV data, several special CNV regions were identified, including gain peaks containing known breast cancer driver genes such as ERBB2 and NOTCH2, as well as the loss peaks containing some known tumor suppressor genes such as PRDM16 and STK11 (CNV focal peak gene annotation)." (PMID 35013309, 2022). "Moreover, the white-to-brown trans-differentiation of omental adipocytes was found in patients affected by pheochromocytoma and breast cancer where mammary tumor stem cells expressed PRDM16, a master regulator of brown adipocyte differentiation." (PMID 33072753, 2020). "To confirm the roles of DLG5 and PRDM16 in LINC00589-regulated CSC-like properties and multiple chemoresistance of breast cancer, we performed mammosphere formation and cell viability assays." (PMID 36309503, 2022).
cardiac hypertrophy (7 papers, 2022 to 2025). "Prdm16 was dispensable for early heart development in mice; however, deficiency led to later-stage cardiac hypertrophy, adverse remodeling, and ultimately heart failure." (PMID 37504561, 2023). "The hearts of mice with cardiac-specific Prdm16 conditional knockout showed abnormal cardiac conduction and phenotypes associated with cardiomyopathy, including cardiac fibrosis and hypertrophy." (PMID 37504561, 2023). "We found that 18 of 24 genes were significantly increased in 5-month-old, female Prdm16CKO compared with controls, supporting the implication of cardiac hypertrophy and oxidative stress in the underlying pathological changes upon the loss of Prdm16." (PMID 35862303, 2022). "Mice with a cardiac loss of Prdm16 had higher heart-to-body weight ratios and upregulated atrial natriuretic peptide, suggesting cardiac hypertrophy." (PMID 35862303, 2022). "Atrial natriuretic peptide (ANP), an established hypertrophy marker, was upregulated in the cardiac ventricular tissues and plasma of Prdm16CKO versus controls, confirming the involvement of a loss in Prdm16 in cardiac hypertrophy." (PMID 35862303, 2022). "Further, our findings suggest that NOS1 is important in reducing BP in mice that present with cardiac hypertrophy due to a cardiac-specific deficiency in Prdm16." (PMID 35862303, 2022). "We have demonstrated that mice with a cardiac-null mutation of Prdm16 present with hypotension and cardiac hypertrophy." (PMID 35862303, 2022). "Mice with cardiac deficiency of Prdm16 present with hypotension and cardiac hypertrophy." (PMID 35862303, 2022). "Deletion of PRDM16 leads to cardiac hypertrophy, fibrosis, mitochondrial dysfunction, and heart failure." (PMID 39684483, 2024). "In this study, using mice with a cardiac-specific deficiency in Prdm16, we confirmed the development of cardiac hypertrophy and noted decreases in BP in Prdm16CKO mice, which we attributed to the upregulation of NOS1." (PMID 35862303, 2022). "Cardiac-specific depletion of PRDM16 results in cardiac hypertrophy and left ventricular noncompaction cardiomyopathy." (PMID 37079380, 2023).
coronary artery disease (7 papers, 2016 to 2026). "reveals that single-nucleotide polymorphisms (SNPs) of PRDM16 are significantly associated with hypertension and cholesterol metabolism (rs2493296), coronary artery disease (rs7413494), and any stroke (rs2455129)." (PMID 37079380, 2023). "Notably, several coronary artery disease-associated SNPs mapped to accessible chromatin regions within the PRDM16 locus in SMCs." (PMID 41107595, 2025).
lung adenocarcinoma (7 papers, 2019 to 2023). A carcinoma that arises from the lung and is characterized by the presence of malignant glandular epithelial cells. "On the other hand, PRDM16, a zinc finger transcription factor hammering the epithelial-to-mesenchymal transition, functions as a suppressor of lung adenocarcinoma metastasis and is associated with patient survival." (PMID 36309503, 2022). "Then we used The Cancer Genome Atlas (TCGA) gene expression and clinical data to further determine whether PRDM16 is associated with other clinical and pathological characteristics of lung adenocarcinoma patients." (PMID 30683132, 2019). "The transcription factor PR domain containing 16 (PRDM16) was found to be downregulated in lung adenocarcinomas, which represses the transcription of Mucin‐4 (MUC4), one of the regulators of epithelial‐to‐mesenchymal transition (EMT) process of cancer cells." (PMID 36504353, 2023). "To investigate the effect of PRDM16 on cell growth and mobility in lung adenocarcinoma, we overexpressed PRDM16 in H1299, Calu-1 and A549 cells or knocked down its expression in H1299 and Calu-1 cells." (PMID 30683132, 2019). "Collectively, these data indicate that PRDM16 functions as a key regulator in inhibiting the metastasis of lung adenocarcinoma cells in vivo." (PMID 30683132, 2019). "Our study discovered that PRDM16 expression was downregulated in lung adenocarcinomas, and its low expression predicted poor prognosis of lung adenocarcinoma patients." (PMID 30683132, 2019). "In this study, we showed that PRDM16 was downregulated in human lung adenocarcinomas, and its low expression predicted high lymph node status, TNM stage grade, and poor prognosis of lung adenocarcinoma patients." (PMID 30683132, 2019). "Consistent with the mRNA level, PRDM16 protein expression was also significantly downregulated in both lung adenocarcinomas and lung squamous cell carcinomas compared with normal lung tissues." (PMID 30683132, 2019). "We found that PRDM16 overexpression inhibited and PRDM16 knockdown promoted the EMT progression of lung adenocarcinoma cells by regulating the expression of epithelial and mesenchymal markers." (PMID 30683132, 2019). "Our findings implicate PRDM16 as an important negative regulator of metastasis in lung adenocarcinomas." (PMID 30683132, 2019). "Taken together, these results indicated that PRDM16 expression level is downregulated in human lung adenocarcinoma tissues and correlated with poor prognosis of lung adenocarcinomas." (PMID 30683132, 2019). "PRDM16 was downregulated in lung adenocarcinomas, and its expression level correlated with key pathological characteristics and prognoses of lung adenocarcinoma patients." (PMID 30683132, 2019). "In this study, we showed that PRDM16 functions as a transcriptional repressor of MUC4 in lung adenocarcinomas." (PMID 30683132, 2019). "The results showed that PRDM16 mRNA level in lung adenocarcinoma and lung squamous cell carcinoma tissues were significantly lower than that in normal lung tissues." (PMID 30683132, 2019). "Among the candidate target genes, MUC4 was elevated in lung adenocarcinoma tissues, and its expression negatively correlated with PRDM16." (PMID 30683132, 2019). "Taken together, PRDM16 suppresses cancer cell EMT by downregulating MUC4 expression in lung adenocarcinoma cells." (PMID 30683132, 2019). "Together, these results demonstrate that PRDM16 functions as a suppressor of tumor metastasis in human lung adenocarcinomas." (PMID 30683132, 2019). "Additionally, GNLY, HOXB7, MRPL33, and PRDM16 were upregulated in bladder urothelial carcinoma, colon adenocarcinoma, lung adenocarcinoma, and rectum adenocarcinoma based on the results of eRic validation." (PMID 37534217, 2023). "However, the mechanisms of MECOM and PRDM16 in prognosis and tumor immune infiltration in lung adenocarcinoma (LUAD) remain uncertain." (PMID 35174083, 2022).
lung adenocarcinoma (continued). "Interestingly, we found only lung adenocarcinoma patients with low PRDM16 expression had shorter overall survival." (PMID 30683132, 2019). "As well as highlighting PRDM16 as a potential biomarker and drug target in lung adenocarcinomas, these data also demonstrate a critical interplay between transcriptional and epigenetic modifications during lung adenocarcinoma progression." (PMID 30683132, 2019). "Besides, we found elevated PRDM16 expression inhibits cancer cell invasion and migration but hardly affects cell proliferation in lung adenocarcinomas." (PMID 30683132, 2019). "Taken together, our study elucidates a novel mechanism of PRDM16 inhibiting the EMT and metastasis of lung adenocarcinoma cells." (PMID 30683132, 2019). "Overexpression of PRDM16 inhibited the cancer cell EMT process by suppressing the transcription of its target gene MUC4, which promoted EMT in lung adenocarcinomas." (PMID 30683132, 2019). "Overexpressing PRDM16 inhibited the epithelial-to-mesenchymal transition (EMT) of cancer cells both in vivo and in vitro by repressing the transcription of Mucin-4 (MUC4), one of the regulators of EMT in lung adenocarcinomas." (PMID 30683132, 2019). "Our findings demonstrate a critical interplay between transcriptional and epigenetic modifications during lung adenocarcinoma progression involving EMT of cancer cells and suggest that PRDM16 is a metastasis suppressor and potential therapeutic target for lung adenocarcinomas." (PMID 30683132, 2019). "Notably, the analysis indicated that low PRDM16 expression was correlated with higher lymph node status and TNM stage grade in lung adenocarcinoma patients." (PMID 30683132, 2019). "Overexpression of full-length PRDM16 or PRDM16-ΔPRD can suppress the transcription of MUC4 which is demonstrated to promote EMT in lung adenocarcinomas, suggesting full-length and PR-lacking PRDM16 exert similar effects on the metastatic ability of cancer cell in lung adenocarcinomas." (PMID 30683132, 2019). "Furthermore, downregulated PRDM16 expression may result from the high methylation levels of its DNA in lung adenocarcinomas but not in lung squamous cell carcinomas." (PMID 30683132, 2019).
prostate carcinoma (7 papers, 2017 to 2024). A carcinoma that arises from epithelial cells of the prostate gland. "While one study suggests that PRDM16 promotes apoptosis in PRDM16,31, 32 several studies indicate its antiapoptotic function in progenitor cells, prostatic cancer cells, and hematopoietic stem cells." (PMID 39309696, 2024). "PRDM16 (MIM: 605557), where rs6658664 is located, is associated with evasion of apoptosis by prostatic cancer cells." (PMID 34993496, 2022). "A recent study using RNA interference screening to interrogate the function of histone methyltransferases and demethylases in prostate cancer cells identified PRDM16 to have a role in allowing cells to evade apoptosis." (PMID 31796844, 2019). "In addition, ADAMTS9-AS1 was found to function as ceRNA, effectively sponging hsa-mir-96 and modulating the expression of PRDM16, thereby influencing tumor cell growth and proliferation in prostate cancer." (PMID 34395250, 2021). "Genes in NK cells (i.e., BCL11B for T-ALL, MAP3K7IP2 for prostate cancer) and in monocytes (i.e., LCK and BCL11B for T-ALL, PDCD1LG2 for Hodgkin’s lymphoma, PRDM16 for AML, CACNA1D for prostate cancer) were found significant in our meta-EWAS." (PMID 38466776, 2024).
heart failure (5 papers, 2024 to 2026). Inability of the heart to pump blood at an adequate rate to meet tissue metabolic requirements. "Based upon the collective results of functional studies, clinical features, and family history, this novel heterozygous frameshift germline variant in PRDM16 was determined to be the cause of the familial cardiomyopathy and heart failure." (PMID 41584850, 2026). "In mouse models, Prdm16 expression is associated with heart failure, LVNC, morphological defects, and perinatal lethality." (PMID 38542214, 2024).